ZNF57 (zinc finger protein 57)
Description:
May be involved in transcriptional regulation.
Synonyms: ZNF424
Tractability: PROTAC: ubiquitination databases record sites on it.
Gene: Protein-coding gene on chromosome 19 (2,900,914 to 2,919,102, forward strand). Ensembl gene ENSG00000171970.
Subcellular location: Nucleus
Subcellular location (Human Protein Atlas): Nucleoli
Gene Ontology:
Molecular function: protein binding; DNA-binding transcription factor activity, RNA polymerase II-specific; RNA polymerase II transcription regulatory region sequence-specific DNA binding
Biological process: regulation of transcription by RNA polymerase II; regulation of DNA-templated transcription
Cellular component: nucleus
Genetic constraint (gnomAD): Loss-of-function variants: 9 observed, 12.62 expected, observed/expected ratio (o/e) 0.71, 90% interval 0.43 to 1.24. The upper end of that interval is the gene's LOEUF score, 1.24, which puts it in group 5 of 6, group 1 being the genes least tolerant of losing a copy. Missense variants: 687 observed, 678.34 expected, observed/expected ratio (o/e) 1.01, 90% interval 0.95 to 1.08. Synonymous variants: 222 observed, 243.21 expected, observed/expected ratio (o/e) 0.91, 90% interval 0.82 to 1.02.
Homologues: Orthologues: chimpanzee ZNF57 (98% identical). Paralogues in human: ZNF709 (43% identical), ZNF791 (42% identical), ZNF433 (39% identical), ZNF14 (39% identical), ZNF700 (38% identical), ZNF441 (38% identical), ZNF44 (37% identical), ZNF878 (37% identical), ZNF823 (37% identical), ZNF442 (36% identical), ZNF799 (36% identical), ZNF443 (35% identical), and 3 more.
Diseases named in the same sentence as ZNF57 in open-access papers:
ZNF57 is named in the same sentence as 8 diseases in open-access papers, as found by Europe PMC text mining. Sharing a sentence is not in itself a finding about the gene and the disease. The quoted sentences say what the papers report.
breast carcinoma (1 paper, 2019). "Zinc finger protein 57 (ZFP57), a member of KRAB-ZFPs, could maintain DNA methylation in embryonic stem cells (ESCs), although its role and underlying mechanisms in breast cancer are not well understood." (PMID 30787268, 2019).
deafness (1 paper, 2012). An inherited or acquired condition characterized by the complete loss of the ability to hear from one or both ears. "If GIPC3 was not known as a cause of deafness we could have concluded that the variant in ZNF57 was causative." (PMID 22363784, 2012).
diabetes (1 paper, 2014). "Interestingly, two different variants in the same gene (called ZFP57 - Zinc finger protein 57) were associated with diabetes in two different breeds." (PMID 26401325, 2014).
hearing loss (1 paper, 2012). "After finding potential regions through autozygosity mapping we identified two novel rare variants to cause hearing loss in this study (GIPC3 p.H170N and ZNF57 p.T443M)." (PMID 22363784, 2012). "ZNF57 is a recently discovered human zinc finger gene which has not been implicated in hearing loss." (PMID 22363784, 2012). "We can speculate that this mutation also may contribute to hearing loss or more likely it might contribute to the susceptibility for another phenotype which was not considered here and that these two variants (ZNF57 p.T443M and GIPC3 p.H170N) are found to co-segregate." (PMID 22363784, 2012).
post-traumatic stress disorder (1 paper, 2021). An anxiety disorder precipitated by an experience of intense fear or horror while exposed to a traumatic (especially life-threatening) event. "Zinc finger protein 57 (ZFP57) has not been previously linked to a neurodegenerative disorder, but its involvement in neurological health is evidenced by research in post-traumatic stress disorder (PTSD)." (PMID 33981329, 2021).
psychosis (1 paper, 2017). "Compared to exposed individuals without psychosis, exposed individuals with psychosis had differential methylation in the region encompassing the gene encoding the zinc finger protein 57 (ZFP57)." (PMID 28406917, 2017).
cancer (1 paper, 2023). A tumor composed of atypical neoplastic, often pleomorphic cells that invade other tissues. "The zinc finger protein 57 (ZFP57) plays crucial functions during the progression of cancer and is reported as a prognostic and therapeutic candidate in a variety of cancer." (PMID 37497403, 2023).
tumor (1 paper, 2025). "In breast cancer, ZNF57 functions as a tumor suppressor by regulating MEST expression to inhibit the Wnt/β-catenin signaling pathway, thereby affecting tumor cell proliferation." (PMID 40636694, 2025).